DCLK1 (doublecortin like kinase 1)
Diseases named in the same sentence as DCLK1 in open-access papers (continued):
Sharing a sentence is not in itself a finding about the gene and the disease.
tumor (continued). "Moreover, studies have confirmed that DCLK1 distinguishes between tumor and normal stem cells in the intestine, and the specific ablation of DCLK1+ CSCs results in a marked regression of polyps without apparent damage to the normal intestine." (PMID 34206989, 2021). "To study the potential stem cell function of Dclk1+ tumor cells, we applied lineage tracing method and examined whether Dclk1+ tumor cells supply the progeny tumor cells within already established mouse PanINs." (PMID 33393460, 2021). "However, with these mouse models, we were unable to perform lineage tracing of Dclk1+ tumor cells, because the Cre-loxP system is already applied to activate oncogenic Kras and because Rosa-reporter has to be activated in another system." (PMID 33393460, 2021). "After twenty years of research, DCLK1 is accepted as a specific marker of TCs and several kinds of CSCs, and is well known for its ability to regulate tumor growth, invasion, metastasis, epithelial-mesenchymal transition (EMT), pluripotency, angiogenesis, and pro-survival signaling." (PMID 33348546, 2020). "Further studies are needed using DCLK1-IN-1 and other specific DCLK1 kinase inhibitors, and an assessment of its ability to influence anti-tumor immunity is especially desirable as the clinical use of kinase inhibitors in conjunction with immune checkpoint therapies is emerging." (PMID 33348546, 2020). "DCLK1 expression level in colon tumor tissues was positively correlated with infiltrating CD8+ T cells (r = 0.28, p < 0.0001), M2 macrophages (r = 0.45, p < 0.0001), Treg (r = 0.45, p < 0.0001), B cells (r = 0.42, p < 0.0001), and M1 macrophages (r = 0.24, p < 0.0001) in COAD." (PMID 31979136, 2020). "DCLK1+ TCs are closely related with tumor initiation and chronic inflammatory diseases." (PMID 33348546, 2020). "In addition, DCLK1 regulates several miRNAs such as miR-let-7a and miR-200a which are known to be involved in tumor growth and EMT." (PMID 31979136, 2020). "Further studies confirmed that DCLK1 distinguishes between tumor and normal stem cells in the intestine and could be therapeutic target for colon cancer." (PMID 32094348, 2020). "Studies confirmed that DCLK1 distinguishes between tumor and normal stem cells in the intestine and could be therapeutic target for colon cancer." (PMID 32094348, 2020). "Indeed, some evidence shows that DCLK1 marked CSCs support growth, metastasis, and escape from eradication in the tumor microenvironment." (PMID 33348546, 2020). "Because DCLK1 associates with tubulins and regulates microtubule dynamics in addition to being a tumor stem cell protein, we investigated whether DCLK1 promotes hepatocyte plasticity via β-catenin regulation." (PMID 32601309, 2020). "Furthermore, several recent studies show that DCLK1 affects tumor growth and metastasis via regulating TAM and immune checkpoint." (PMID 33348546, 2020). "By performing multivariate analysis to control for relevant clinical factors including age, gender, stage, T, N, M, and tumor location, we found that DCLK1 is an independent factor which can be used to predict poor DSS (p = 0.009) and PFI (p = 0.024), but not OS (p = 0.18) in CRC." (PMID 31979136, 2020). "Targeting DCLK1 with these mAbs in xenograft mouse models from KRASG12D mutant human cell lines AsPC-1 or SW1990 or in the KPC mouse model led to significant inhibition of the tumor growth." (PMID 31467540, 2019). "Knockdown of DCLK1 or application of small molecule kinase inhibitors for DCLK1 could result in a delay of tumor development by down-regulating miRNAs downstream pluripotency transcription factors, EMT and critical oncogenic pathways." (PMID 29246000, 2017). "In pancreatic cancers, DCLK1 positive cells displayed increased sphere forming and tumor initiating capacity, and enhanced epithelial-mesenchymal transition (EMT), a process closely linked to the acquisition of stem cell properties, via regulation of microRNA biogenesis." (PMID 26621833, 2016).
tumor (continued). "DCLK1 plays a biological role in gastrointestinal tumors, and small molecule inhibitors of DCLK1 may be useful as anti-tumor stem cell drugs in these tumors." (PMID 26764906, 2016). "The measurement of DCLK1 levels in serum samples and of its expression in CTCs could hence be an important marker for tumor malignancy and EMT." (PMID 27529216, 2016). "DCLK1 mRNA levels in the tumor tissues are significantly higher than that in normal control." (PMID 25723399, 2015). "We evaluated the effects of DCLK1 knockdown on Huh7.5-derived tumor xenograft growth." (PMID 26468984, 2015). "If these findings are confirmed, the development of targeted agents against DCLK1+ tumor stem cells may inhibit PDAC progression and metastasis and ultimately extend patient survival." (PMID 25723399, 2015). "In addition, we have also presented evidence that DCLK1 overexpression alters expression of an array of genes, which are involved in inflammation and tumor growth." (PMID 25948779, 2015). "Notably, NANOG was expressed in high quantities in all the tumor tissues studied, showing clear co-expression with DCLK1." (PMID 26622789, 2015). "We evaluated the expression of levels of DCLK1 and cMYC in tumor xenografts treated with siRNAs." (PMID 26468984, 2015). "Although the precise tumor-promoting mechanism of DCLK1 has yet to be fully elucidated, the DCLK1-mediated downregulation of the expression of tumor-suppressing microRNAs (miR), such as miR-145, miR-200 and let-7a, has been demonstrated to be a possible mechanism." (PMID 26622789, 2015). "These assertions, although speculative, are strengthened by the recent report that DCLK1 marks tumor stem cells in ApcMin/+ mice, supporting the functional significance of DCLK1 in neoplasia." (PMID 26468984, 2015). "In addition, more than 50% of circulating tumor cells isolated from the blood of KPC mice are DCLK1 positive." (PMID 25723399, 2015). "DCLK1 mRNA levels were significantly higher in the tumor samples compared to normal controls." (PMID 25723399, 2015). "Similarly, we found that DCLK1 is highly expressed in the CSC-rich hFL-HCC tumour line and primary hFL-HCCs, but lowly expressed in all normal hepatic maturational lineage stages including hBTSCs and hHpSCs." (PMID 26437858, 2015). "However, as the number of tumor samples and the tumor grade were limited, further large-scale studies are required to determine the role of DCLK1 in NETs more precisely." (PMID 26622789, 2015). "Given DCLK1’s tumor stem cell marker status, a strong understanding of its biological role and interactions in gastrointestinal tumors may lead to discoveries that improve patient outcomes." (PMID 24885928, 2014). "The results of this study suggest that small molecule inhibitors of DCLK1 kinase should be further investigated as they may hold promise as anti-tumor stem cell drugs." (PMID 24885928, 2014). "Therefore, our data combined with previous findings that Dclk1 knockdown induces tumor growth arrest suggesting that Dclk1 is critical for intestinal neoplasia." (PMID 25211188, 2014). "Additionally, we also observed a significant (>40%) downregulation of OCT4 and SOX2 at the mRNA level following the knockdown of DCLK1 in AsPC-1 tumor xenografts." (PMID 24040120, 2013). "Furthermore, we wanted to investigate the effect of DCLK1 knockdown on expression of miR-200b and c in AsPC-1 tumor xenografts." (PMID 24040120, 2013). "In this report, we have demonstrated that in addition to regulating several tumor suppressor miRNAs and downstream oncogenic targets, DCLK1 inhibition results in upregulation of miRNAs that negatively regulate several key pluripotency and pro-angiogenic factors." (PMID 24040120, 2013). "Similarly, here we observed a significant induction (1.5-fold) of pri-miR-143/145 cluster miRNA and pri-miR-145 miRNA following the knockdown of DCLK1 in AsPC-1 tumor xenografts." (PMID 24040120, 2013).
tumor (continued). "Dclk1+ cell lineage ablation causes tumor regression without damage to the normal intestine tissue." (PMID 40072059, 2025). "We previously revealed that DCLK1 overexpression was correlated with PCa tumor aggressiveness and might effectively predict poor biochemical recurrence-free survival outcomes in patients after radical prostatectomy 10, but the related underlying molecular mechanism remains obscure." (PMID 39781521, 2025). "This work distinguishes DCLK1 and miRNAs’ potential role in different axes promoting inflammation to tumor progression and may serve to identify biomarkers for tracking the progression from pre-neoplastic states to HCC in chronic liver disease patients as well as provide targets for treatment." (PMID 38928187, 2024). "This not only highlights that the catalytic activity of DCLK1 may regulate additional tumor-promoting cellular processes, but also argues for a need to develop (isoform) selective DCLK1 inhibitors to dissect the contribution of DCLK1 kinase activity to tumorigenesis." (PMID 36979969, 2023). "Others have identified that a small proportion of DCLK1+ tuft cells are Lgr5+ (stem cell marker) and may act as tumour stem cells during intestinal tumorigenesis, and that DCLK1 expression readily differentiates intestinal tumour stem cells from normal stem cells." (PMID 36263033, 2022). "Furthermore, we wondered whether DCLK1 inhibitor suppressed DCLK1‐mediated 5‐fluorouracil resistant CRC cells in subcutaneous xenograft tumour models." (PMID 35522902, 2022). "Moreover, this process might be connected to DCLK1 regulatory activity on EMT, considering EMT is associated with immune checkpoint during tumor development." (PMID 34453639, 2021). "Also, DCLK1 expression in normal and tumor stem cells in the intestine appear to be different and therefore, may be a potential therapeutic target for cancer." (PMID 31992775, 2020). "Finally, it is tempting to speculate that observed changes result from the eradication of tumor cells secreting DCLK1, but further investigations are necessary to test this hypothesis." (PMID 30899515, 2019). "Furthermore, tumours formed by GR cells treated with 2‐DG showed a decreased staining for DCLK1." (PMID 28244691, 2017). "Furthermore, tumours formed by 2‐DG‐treated cells showed reduced staining of DCLK1." (PMID 28244691, 2017). "However, tumours originated from GR cells had enhanced staining for DCLK1." (PMID 28244691, 2017). "Moreover, the possibility that DCLK1 may mark a population of tumor stem-like cells in RCC should be further investigated in light of these findings." (PMID 25605241, 2015). "Thus, DCLK1 may exert influence on immune suppression, tumor microenvironment, and tumor-stromal interactions by modulating S100A9 and NFκB activities." (PMID 25948779, 2015). "Collectively, our results support the idea that overexpression of DCLK1 promotes a stem cell-like phenotype by inducing LATS1-mediated YAP signaling activation, ultimately leading to tumor growth and progression in PCa." (PMID 39781521, 2025). "Overall, DCLK1 promotes MAPK pathway activation via KRAS upregulation and p62 accumulation, thereby supporting tumor growth, stress adaptation, and potentially aiding intestinal epithelium regeneration after radiation injury." (PMID 40563698, 2025). "Apc deletion specifically in DCLK1+ cells can initiate tumors when combined with DSS damage, further supporting the role of these cells as tumor initiating cells in the gut." (PMID 37863104, 2024). "Subsequently, to further investigate the function of DCLK1 in augmenting tumor growth in vivo, we employed BALB/c nude mice to establish a subcutaneous transplant tumor model." (PMID 38980538, 2024). "DCLK1 also promotes β-catenin signaling by stabilizing CCAR1, thereby enhancing tumor cell stemness and mediating 5-fluorouracil resistance in CRC." (PMID 38254219, 2024).
tumor (continued). "The results demonstrated that tumor tissues from the RBE CTRL group exhibited lower E-cadherin expression and higher Vimentin expression compared with the RBE DCLK1-KO group." (PMID 38980538, 2024). "Firstly, our IHC results demonstrated that DCLK1 was significantly upregulated in human CCA tissues, but barely detected in non-tumor controls." (PMID 38980538, 2024). "The study showed that DCLK1-based CAR-T cells exhibited cytotoxicity against CRC cells and inhibited CRC tumor growth in vivo." (PMID 37420216, 2023). "This was dependent on the DCLK1 phosphorylation of XRCC5 and the co-option of the inflammatory tumor microenvironment (TME)." (PMID 38003596, 2023). "Considering that the efficacy ICIs requires CD8+ T cells infiltrations in tumor, we performed TIDE analysis based on FUSCC dataset to predict the correlation between DCLK1 expression levels and the responsiveness of ICIs in TNBC patients." (PMID 37069669, 2023). "Studies on response to inflammation reported that inflammation is progressed upon DCLK1 expression in GI cancer cells that serve as EMT precursors and tumor formation." (PMID 36250024, 2022). "In parallel, the DCLK1-IN-1 treatment dramatically reduced the PGE2 levels in plasma and primary tumor tissue." (PMID 35910805, 2022). "Preclinical studies have proved the biological functions of DCLK1 as a requisite factor in proliferative potential, angiogenesis, epithelial-mesenchymal transition (EMT), tumor invasion, and metastasis in solid tumors particularly in CRC." (PMID 35717205, 2022). "RT‐qPCR and Western blot analyses were conducted to determine the expression of let‐7i, KDM3A, DCLK1 and FXYD3 in tumours." (PMID 33350586, 2021). "Although these studies demonstrated a role of Dclk1+ cells in PDAC initiation in vivo and tumor stem cell properties of Dclk1+ cells in vitro, natural behavior and tumor/CSC activity of Dclk1+ cells within established tumors in vivo have been unclear." (PMID 33393460, 2021). "Of the 16 kinases originally identified in the tumour dataset, 6 were also found to be differentially expressed in the cell line panel: AKT3, MYLK, PRKD1, AXL, NUAK1 and DCLK1." (PMID 33673003, 2021). "A recent study correlated EMT with an increased risk of recurrence and poor OS in RCC patients based on the expression of DCLK1 (a serine/threonine kinase involved in microtubule-mediated neuronal migration and morphogenesis) in RCC tumours." (PMID 34099013, 2021). "As a CAR-T target, DCLK1 single-chain antibody variable fragment (CBT-511), showed a prominent cytotoxic effect against tumor cells and reduced tumor growth in CRC." (PMID 33348546, 2020). "C-B and C-I downregulated the expression of DCLK1, CD44 and LGR5 in HCT116 tumor samples relative to the vehicle control." (PMID 31992775, 2020). "In addition, our study found that Notch1 was significantly inactivated in the presence of DCLK1 knockdown, which was consistent with the previous study, indicating that DCLK1 may regulate tumour metastasis and the EMT process of GC via mediation of the Notch1 signalling pathway." (PMID 32423385, 2020). "To further study the relationship of DCLK1 to immune cell subtypes in the TME, we fragmented the composition of immune cells in tumor tissues of COAD and STAD using quanTIseq." (PMID 31979136, 2020). "Here, we found that both C-B and C-I inhibit colonosphere formation and the expression of all three CSCs markers DCLK1, LGR5, and CD44v, both in cell culture and in vivo in mouse tumor xenograft models." (PMID 31992775, 2020). "Doublecortin-like kinase 1 (DCLK1), a novel stem cell marker specific to tumor cells, has been identified." (PMID 31530793, 2019). "Here, we report the role of DCLK1 in KRAS-PI3K-MTOR signaling pathway and its implications for chemoresistance and tumor growth." (PMID 31467540, 2019). "Our proprietary DCLK1 mAb, CBT-15, recognizes a 13 amino acid sequence (extracellular domain) of the tumor-specific DCLK1 isoforms 2 and 4 with a binding affinity of < 1 nM Kd." (PMID 31878090, 2019).
tumor (continued). "To confirm the in vivo efficacy of DCLK1 CAR-T cells in CRC cell lines, we generated LoVo CRC cell line-derived tumor xenografts in NSGTM mice." (PMID 31878090, 2019). "Emerging evidence suggests that DCLK1, a well‐established putative pancreatic CSC marker, regulates the EMT phenotype 22 and facilitates tumour invasion and metastasis." (PMID 28244691, 2017). "Circulating tumor cells were isolated from KPCY mice and approximately 52% of these cells were positive for Dclk1 staining." (PMID 25723399, 2015). "Another proposed mechanism involves the DCLK1-dependent induction of vascular endothelial growth factor receptor and epithelial-mesenchymal transition (EMT)-related factors in tumor cells." (PMID 26622789, 2015). "To demonstrate a regulatory role of DCLK1 in HCC tumorigenesis, we generated tumor xenografts and examined the effects of treatment with siRNAs." (PMID 26468984, 2015). "Doublecortin-like kinase 1 (DCLK1), a biomarker of colorectal CSCs, induces the expression of CXCL1 and CXCL2 through the ERK pathway, facilitating the recruitment of MDSCs into an immunosuppressive TME and promoting tumor growth." (PMID 41368628, 2025). "Taken together, the data presented above support the speculation that overexpression of DCLK1 promotes stem cell-like characteristics by inducing LATS1-mediated YAP signaling activation, ultimately leading to tumor growth and progression in PCa." (PMID 39781521, 2025). "D-peptide 1 effectively suppressed tumor growth and stemness in vitro and in vivo potentially by modulating pGSN or other PPI binding without complete disruption, underscoring the therapeutic potential of targeting the DCLK1 NKEBD." (PMID 40162222, 2025). "Analysis of lysates from ADAM10 KO and WT U251 cells revealed changes consistent with those identified above, including downregulation of stem cell markers, such as DCLK1 and ALDH1L2, in keeping with the effects on Notch and Wnt pathway members, and the increased differentiation noted in tumours." (PMID 41226720, 2025). "Collectively, our results support the idea that overexpression of DCLK1 promotes the acquisition of a stem cell-like phenotype by inducing large tumor suppressor homolog 1 (LATS1)-mediated YAP signaling activation, ultimately leading to tumor growth in PCa." (PMID 39781521, 2025). "In vivo experiments showed that anti-DCLK1 CAR-T-cell treatment of LOVO xenograft mice inhibited tumor growth by more than 42% without inducing obvious toxicity." (PMID 38254219, 2024). "Studies have shown that both mouse and human PanIN and PDAC express DCLK1, and DLK1 may mark tumor-initiating cells in a variety of tumor types." (PMID 39839479, 2024). "Our results indicated that the PI3K/AKT/mTOR signaling pathway inhibitor could reverse DCLK1-mediated tumor progression, suggesting that CCA populations with high DCLK1 expression may benefit from therapies targeting the PI3K/AKT/mTOR pathway." (PMID 38980538, 2024). "Recent studies have discovered that stem cell markers, such as doublecortin-like kinase (DCLK1) and RNA modification by methyltransferase-like 3 (METTL3), play a role in recruitment of CXCR2+ MDSCs to modulate tumor immunity through the CXCL1-CXCR2 axis in CRC mouse models." (PMID 38750114, 2024). "Our results revealed that DCLK1 knockout significantly inhibited subcutaneous tumors growth in immunocompetent mice but not immunocompromised nude mice, which implied the strong negative correlation between DCLK1 and anti-tumor immune." (PMID 37069669, 2023). "We found that high DCLK1 and IL-6 expression predicted shorter relapse-free survival (RFS) in TNBC (n = 392) but not in luminal A (n = 522), luminal B (n = 332) and HER2 (n = 315) subtypes, which suggested the dominant roles of DCLK1 and IL-6 in TNBC tumor recurrence." (PMID 37069669, 2023).